SSTR2 (somatostatin receptor 2)
Diseases named in the same sentence as SSTR2 in open-access papers (continued):
Sharing a sentence is not in itself a finding about the gene and the disease.
tumor (continued). "The observed variation in SSTR2 expression between tumor lesions suggests that heterogeneous target expression may have been the reason for treatment failure in this patient’s case." (PMID 39324010, 2024). "After treatment, the primary tumor displayed clonal heterogeneity, with a cluster of undifferentiated NB cells with low SSTR2 expression among a majority of differentiated, ganglioneuroma-like cells with a high SSTR2 expression." (PMID 39324010, 2024). "PSC-PEG2-TOC (VMT-α-NET) is a novel somatostatin receptor subtype 2 (SSTR2) targeting peptide for the treatment of neuroendocrine tumors (NET) that shows rapid tumor accumulation, high tumor retention, and fast renal excretion with the potential for low nephrotoxicity." (PMID 37991526, 2024). "Finally, CCK2R tumor imaging ([177Lu]Lu-PP-F11N SPECT/CT) was compared with somatostatin receptor subtype 2 (SSTR2) PET/CT imaging ([68Ga]Ga-DOTATOC or [68Ga]Ga-DOTATATE) in all patients." (PMID 38581480, 2024). "Hypotheses about faster release of radiocopper-labeled NODAGA-TATE variants from tumor cells compared to [177Lu]Lu‐DOTA-TATE may address possible differences in downstream trafficking and metabolic fate of the ligand-SSTR2 complex." (PMID 39310112, 2024). "It has been hypothesized that SSTR2 heterogeneity may affect clinical outcome and play an important role in predicting tumor response to therapy." (PMID 37444593, 2023). "All GLP-1R-negative and most (69%) GLP-1R-positive tumours expressed SSTR2 subtype (p = 0.244)." (PMID 37894845, 2023). "Findings from preclinical studies using PPGL cell lines and tumor models may provide further leads toward the identification of SSTR2 regulatory mechanisms." (PMID 36946182, 2023). "Moreover, the tumor also expressed SSTR2, further extending the monitoring and therapeutic window of opportunities for EBV-associated LESCG." (PMID 37847488, 2023). "Blocking studies further confirmed SSTR2-specific tumour accumulation." (PMID 37049918, 2023). "However, recent studies have demonstrated in prospective placebo-controlled and randomized studies that SSAs (octreotide and lantreotide) also reduce tumor progression in NECs displaying SSTR2." (PMID 37568733, 2023). "It has been shown that SSTR2 expression in pancreatic and SI-NENs correlate with a better prognosis and longer overall survival and that the benefits of SSA therapy on progression-free and overall survival are linked to the positive SSTR status of the tumour." (PMID 36980746, 2023). "According to the authors, this result may be related both to DOTATATE’s higher affinity for SSTR2 (which is the type most overexpressed in PPGLs) and to the longer half-life of 177Lu and, consequently, prolonged residence time within the tumor lesions." (PMID 37111596, 2023). "Furthermore, in comparison to low-grade tumours, relatively high expression of SSTR2 and SSTR3 has been reported in low intermediated groups of SCLC." (PMID 38203605, 2023). "Our study investigated intertumoral heterogeneity of WHO grade, SSTR2 status, expression of basal diagnostic markers of SI-NET, and the immunogenic microenvironment in a series of multifocal NETs comprising 146 individual neoplasms from 28 patients." (PMID 36010956, 2022). "In addition, FLNA resulted critical in mediating the inhibition of two key events in tumor development, cell migration and the increase of cell adhesion, both induced by SSAs-activated SSTR2." (PMID 37435454, 2022). "Although expression of SSTR2 (score 2+/3+) was present in at least one investigated tumor in most patients with multifocal SI-NETs, we observed discordant SSTR2 expression in 43% of patients and two individuals in whom all investigated NETs were SSTR2-negative or only very weakly positive." (PMID 36010956, 2022). "SSTR2 was previously demonstrated as a tumour suppressor that inhibits cell proliferation." (PMID 35633292, 2022).
tumor (continued). "With tumor progression to higher histological grades, hindgut NETs could be more deviated from their normal counterparts and harbor higher SSTR2 expression (left red arrow)." (PMID 35159042, 2022). "Therefore, if the tumor cells expressing SSTR2 are spread out in 3D space, perhaps due to dead cells, extracellular fibrosis or other structures in the voxel, the SUV will go down, and as such the Krenning score will go down." (PMID 35198446, 2022). "SSTR2 inhibits cell proliferation, serving as a tumour suppressor in non‐neuronal cells." (PMID 35633292, 2022). "A third patient with a scan of Krenning score 3 had strong SSTR2 expression in 10% of tumor cells." (PMID 35198446, 2022). "Finally, although it makes it extremely useful for our purpose, it is a limitation of this study that the high and homogenous SSTR2 expression in the NCI-H69 tumor model cannot be fully interpolated to human tumors." (PMID 35745856, 2022). "Despite this, BASS labeled with 64Cu via the chelator 4, 11-bis(carboxymethyl)-1,4,8,11-tetraazabicyclo [6.6.2]hexadecane (CB-TE2A) (64Cu-CB-TE2A-BASS) showed a compromised tumor uptake compared to the agonist 64Cu-CB-TE2A-octreotate in SSTR2-positive AR42J xenografts." (PMID 36569154, 2022). "The few critical factors, which influence the choice of the first modality in the setting of metastatic pNET are tumor biology, reflected by the grading, and SSTR density— SSTR2 density mostly drives the susceptibility of pNET to somatostatin receptor therapies." (PMID 35326628, 2022). "G68-DOTATATE PET scan may be useful to predict expression of SSTR2 in tissue; however, it cannot predict whether SSTR2 is expressed in tumor cells or other cells such as inflammatory cells." (PMID 35198446, 2022). "Weak positive staining for somatostatin-receptor 2 (SSTR2) was detected in 10% of the tumor cells." (PMID 35789568, 2022). "This can be attributed to a ‘sink’ effect influenced by overexpression of SSTR2 in the tumor." (PMID 36559060, 2022). "The recently reported “tumour sink effect” highlights an inverse dependence of renal and tumour uptake of [68Ga]Ga-DOTATATE in NET patients with SSTR2-positive tumours and of [177Lu]Lu-PSMA I&T in prostate cancer patients who underwent a single time point PET-CT for staging." (PMID 35347483, 2022). "Besides symptomatic management, recent research has demonstrated that SSAs display antiproliferative effects and inhibit tumor growth through SSTR2." (PMID 36555512, 2022). "Tumor uptake on SSTR2 imaging is correlated with SSTR2 expression on immunohistochemistry." (PMID 35368455, 2022). "The expression of SSTR2 in whole tumors can reflect the tumor burden." (PMID 35368455, 2022). "Thereafter, SSTR2 expression was also evaluated in tumor tissue." (PMID 35745856, 2022). "Somatostatin receptor 2 (SSTR2) is expressed by many tumor types including the majority of NB tumors, with expression in clinical samples ranging from 77 to 100% depending on the method of detection, and there is a negative correlation between SSTR2 expression and clinical risk." (PMID 33630166, 2021). "Tumor tissue was defined by cell staining for SSTR2 in the cell membrane and Bcl2 in the cytoplasm." (PMID 33962620, 2021). "Tumour expression of somatostatin receptor subtype 2 (SSTR2) using immunohistochemistry was performed on 54 tumour samples including samples from 8/12 (66.6%) patients who took part in the imaging study and 46 tumour samples from individuals not included in the imaging study." (PMID 33443647, 2021). "Overexpressed-SSTR2 in pancreatic human NETs demonstrated that fluorescence of SSTR2 receptor-mediated uptake was observed at the macro-, meso-, and microscopic scales, thus displaying specific SSTR2-digital image pathological findings, such as tumor boundaries and location." (PMID 33796080, 2021).
tumor (continued). "Moreover, in the tissue sections of SSTR2-positive NCI-H69 tumor-bearing mice, treated with 800CW-TATE the NIR-fluorescence signal (red) co-localized (yellow-orange), to a considerable extent with the TUNEL signal (green) indicating dead cells." (PMID 33970376, 2021). "This SSTR2 upregulation may lead to increased therapeutic efficacy as more functionalized micelles will be targeted to the tumor cells." (PMID 33085037, 2021). "Among 42 patients that had received PRRT, 10 had at least one tumor with low SSTR2 expression." (PMID 33922482, 2021). "SSAs, like PRRT, have a high affinity to SSTR2 and therefore might act competitively in binding the tumor cells of NETs or lead to saturation." (PMID 34681229, 2021). "SSTR2 expression can be assessed with immunohistochemistry (IHC) in tumor samples." (PMID 33922482, 2021). "Additionally, future immunohistochemical investigation utilizing SSTR2 stains and those investigating vascularity on resected tumor samples can assist in supporting the results of this study." (PMID 35155210, 2021). "Previous studies have reported high-level expression of the somatostatin receptor 2 (SSTR2) subtype in GIST tumours with unknown mutational status and that GIST tumour sites can be identified with 111In-Octreotide scintigraphy in 3/6 cases." (PMID 33443647, 2021). "Several tumor samples only showed mild SSTR2 staining but high uptake on [68Ga]Ga-DOTATATE imaging." (PMID 33916640, 2021). "This hypothesis is based on the following assumptions: (i) SSTR2 expression in SI-NET correlates among a patient’s lesions, i.e., the presence of one tumor with a low SSTR2 expression indicates that other lesions also could have a low SSTR2 expression." (PMID 33922482, 2021). "The therapeutic activity of LuTate requires tumour expression of its target receptor, SSTR2." (PMID 32576907, 2020). "Nevertheless, the expression level of SSTR2 between normal tissues and tumor tissues is different." (PMID 33014821, 2020). "However, the biological impact of SSTR2 is unclear; with evidence in the literature supporting both a pro‐tumour survival signal and cancer growth inhibition." (PMID 32666581, 2020). "A previous study using seven CCA tumor tissues found that all CCA tumors expressed mRNA of SSTR2." (PMID 32069926, 2020). "Cell lines that expressed SSTR2 in vivo were implanted into nude mice and once the tumours became well-established the animals were injected intravenously with 20 MBq LuTate and the tumour response evaluated." (PMID 32576907, 2020). "Finally, the in vivo anticancer efficacy study demonstrated that the SSTR2/CXCR4 dual-targeted EV-Ver-A/DM1 is more effective to inhibit NE tumor growth than the single targeting and single drug." (PMID 33187322, 2020). "However, even at the 48 and 72 h, tumor fluorescence was still higher than healthy tissues with endogenous SSTR2 expression (pancreas, small intestine, lung, and stomach)." (PMID 33300316, 2020). "In addition, histological analysis using 27 CCA tumor tissues detected SSTR2 from only 30% of CCA tumors." (PMID 32069926, 2020). "However, as SSTR2 is dominant for targeting in terms of both tumor expression as well as somatostatin analogue affinity, the contribution of other SSTRs to the imaging success would probably be limited." (PMID 33120925, 2020). "Our data demonstrate that the expression and cellular localisation of SSTR2 differed depending on the context in which cells were grown, with high membrane localised SSTR2 expression seen in tumour xenografts while lower, predominantly cytoplasmic SSTR2 expression seen in cells cultured in vitro." (PMID 32576907, 2020). "Furthermore, understanding the heterogeneity of SCLC tumors and how SSTR2+ subsets contribute and signal in the tumor is vital to predict which patients will have the best response to treatment." (PMID 31413814, 2019). "All patient tumours were positive for chromogranin A, synaptophysin, serotonin, SSTR2 and Hsp90." (PMID 30730850, 2019).
tumor (continued). "This suggests potential heterogeneity in tumor response from tumor to tumor and also suggests that antibody drug conjugates targeted at SSTR2 may only lead to enriched killing of SSTR2+ cell subpopulations." (PMID 31413814, 2019). "However, when patients were treated SST analogues after surgical resection of HCC with high expression of SSTR2 and 5, tumor recurrence rate was significantly lower." (PMID 31569719, 2019). "Interestingly, the expression of pituitary tumor-specific receptors, SS receptors type 2 (SSTR2) and 5 (SSTR5) or DRD2 has been detected in cells in the spheres." (PMID 31708878, 2019). "All xenografted tumours were strongly stained for SSTR2 and Hsp90α/β." (PMID 30730850, 2019). "The limited efficacy of pasireotide may reflect the unique biology of pasireotide binding to SSTR2 subtype, which has been shown to be critical for the growth inhibitory effects of somatostatin signaling pathway in various tumor types." (PMID 30807575, 2019). "All patient tumours were strongly positive for SSTR-2 at the cell membrane." (PMID 29858948, 2018). "PEN221 is now in phase 1 clinical trials for SSTR2-expressing tumours." (PMID 31544868, 2018). "Even if each tumor expresses more than one subtype of SSTRs, SSTR-2 is the most regularly observed." (PMID 29949880, 2018). "The present study characterized mouse strain-specific metastatic phenotypes of intravenously induced luciferase-expressing MPCLUC/GZ allografts, in particular with regard to metastatic spread, tumor progression, catecholamine excretion and somatostatin type 2 (SSTR2) receptor status." (PMID 30288966, 2018). "Artificially synthesized somatostatin analog (SSTA) such as octreotide (OCT) could specifically bind to SSTR2 to achieve the purpose of targeting tumor cells with SSTR2 expression." (PMID 30621480, 2018). "Indeed, it has recently been reported, that treatment of BON-1 cells with HDAC inhibitors can potently induce SSTR2 expression coinciding with a profound proliferative arrest of the tumor cells." (PMID 28800359, 2017). "In summary, the IHC score of SSTR2 is a valuable indicator for the prediction of both biochemical and tumor size response to SSA and could be a clinically useful index to predict the short-term efficacy of SSA treatment in acromegalic patients." (PMID 28396686, 2017). "Notably, the reduction of tumor volume was significantly correlated with the SSTR2 score (r = 0.367, P = 0.005)." (PMID 28396686, 2017). "Some other studies also revealed that up-regulation of MMP-9 expression enhanced the chemotherapeutic resistance, and SSTR2 could suppress tumor growth and metastasis by inhibition of MMP-2 and -9 expressions indirectly." (PMID 27825139, 2016). "While activation of Notch1 is able per se to suppress NET tumor growth and is associated with reduction of NET tumor markers, SSTR2 up-regulation has been used to synergistically increase the cytotoxicity of a SSTR-targeting camptothecin-somatostatin conjugate." (PMID 27418145, 2016). "SSTR2 expression in tumor tissues was detected by IHC using the monoclonal antibody against SSTR2." (PMID 27825139, 2016). "Chemotherapy might affect the SSTR2 expression on tumour cells, on which PRRT depends for targeting of radionuclides, for example." (PMID 26553049, 2015). "In this patient, the expression of SSTR2 was demonstrated on both primary tumour and metastases, and three months of treatment with lanreotide SR 30 mg administered twice a month induced a decrease in the size of the mediastinal nodes and complete disappearance of the lung nodes." (PMID 25225571, 2014). "Moreover, the tumour showed the expression of somatostatin receptor type 2 (SSTR2), implicating responsiveness to somatostatin analogue therapy." (PMID 25520848, 2014). "How SSTR2 might regulate tumor spreading is less clear, but published data suggests a mechanism promoting cell-cell adhesions." (PMID 25010045, 2014). "In tumor cells, activation of SSTR2 and ORs inhibit the phosphorylation of EGFR." (PMID 24059654, 2013).
tumor (continued). "In this study, we compare gene expression in tumors after intra-arterial and intra-tumoral delivery of a SSTR2-based reporter gene using a rabbit VX2 tumor model and evaluate the importance of morphology on quantification of gene expression after in vivo gene transfer." (PMID 23762226, 2013). "Furthermore, SSTR2 interfere with PI3K signaling via disruption of the SSTR2/p85 subunit complex consequently inhibiting the cell proliferation and tumor growth." (PMID 24059654, 2013). "Moreover, the physiological response of tumor cells upon activation of SSTR2/ORs parallel the changes seen in downstream signaling." (PMID 24059654, 2013). "Furthermore, this is the first study to compare tumor directed IA versus IT gene delivery and to illustrate SSTR2-based reporter imaging in a large animal model." (PMID 23762226, 2013). "Our study provides new insights in SSTR2/SSTR3 mediated signaling which might help in better understanding of the molecular interactions involving SSTRs in tumor biology." (PMID 22651821, 2012). "Moreover, the heterodimerization of SSTR2 with mutated SST5TMD4 modulates SSTR2 regulated downstream signaling and SST mediated anti-tumor effects." (PMID 24281555, 2012). "However, it should be notedthat such effects were observed mostly in tumor cells which overexpress the SSTR2.In keratinocytes, the SSTR2 is likely to be expressed at physiological levels, whichmay not be sufficient to inhibit proliferation." (PMID 21589940, 2011). "This conjugate demonstrated its broad and excellent anti-tumor activity by targeting SSTR2-specific tumor tissues, supporting that short peptides and their analogs may be applied as ideal drug-delivery carriers to improve the traditional chemotherapy." (PMID 21892324, 2008). "Both SSTR2 mRNAs and proteins were detected in all these tumor cell lines." (PMID 21892324, 2008). "Further, SSTR2 proteins (~64 kD) were detected in all 5 tumor cells by western blot." (PMID 21892324, 2008). "The expression of SSTR2 in all tested tumor cells was identical to previous reports that SSTR2 is abberantly expressed in these tumor tissues, thus confirming that SSTR2 could be used as a specific target for JF-10-81 to treat these receptor-positive tumors." (PMID 21892324, 2008). "Furthermore, understanding the interaction between SSTR2 signaling and the tumor microenvironment—including stromal remodeling, immune evasion, and angiogenesis—could reveal combinatorial vulnerabilities that enhance treatment outcomes." (PMID 41002582, 2025). "Nevertheless, the strong predictive value of PET-determined gross total resection in this study suggests that the absence of residual SSTR2-expressing tumor may supersede some molecular risk features in guiding postoperative management decisions." (PMID 41497451, 2025). "Immunostaining showed that the tumor was neuroendocrine, as they were positive for Chromogranin A (CgA), Synaptophysin (Syn), CD56, CK, CK7, CK8, Epithelial membrane antigen (EMA), Recombinant Somatostatin Receptor 2(SSTR2), insulinoma-associated protein 1(INSM1), KI-67 was 70 %." (PMID 40034377, 2025). "Here, we analyzed SSTR2 gene expression and its associations with genomic features, established biomarkers predicting of immune response, and the tumor immune microenvironment in a cohort of ONB, SNUC, and SNEC tumor samples (26, 13, and 8 samples, respectively) from a real-world database." (PMID 39682120, 2024). "However, with a cell-surface receptor as the target, this SSTR2 targeted PET is theoretically expected to be less informative on the metabolic state of a tumor, which might be a limitation in the detection of tumor proliferation." (PMID 38720053, 2024). "Hence, while SSTR2 qualifies as a gene involved in growth arrest in accordance with the proposed anti-tumor function, the reverse may be true for SSTR5." (PMID 39682758, 2024).